LINC02178 (long independently transcribed non-coding RNA 2178)
Gene: Long non-coding RNA gene on chromosome 16 (50,390,894 to 50,397,277, reverse strand). Ensembl gene ENSG00000261092.
Diseases named in the same sentence as LINC02178 in open-access papers:
LINC02178 is named in the same sentence as 1 disease in open-access papers, as found by Europe PMC text mining. Sharing a sentence is not in itself a finding about the gene and the disease.
LINC02178 shares sentences with these, for which no sentence is quoted: cancer (1 paper).